SCGB2B3P (secretoglobin family 2B member 3, pseudogene)
Synonyms: C2B; SCGB4A3P
Gene: Transcribed processed pseudogene on chromosome 19 (34,645,662 to 34,646,070, forward strand). Ensembl gene ENSG00000269811.
Diseases named in the same sentence as SCGB2B3P in open-access papers:
SCGB2B3P is named in the same sentence as 1 disease in open-access papers, as found by Europe PMC text mining. Sharing a sentence is not in itself a finding about the gene and the disease.
SCGB2B3P shares sentences with these, for which no sentence is quoted: tumor (1 paper).